TIAM1 (TIAM Rac1 associated GEF 1)
Diseases named in the same sentence as TIAM1 in open-access papers (continued):
Sharing a sentence is not in itself a finding about the gene and the disease.
tumor (95 papers, 2006 to 2025). "Mechanistically, miR-10a-5p directly targets TIAM1, an oncogene associated with tumor progression, leading to its downregulation." (PMID 39796267, 2025). "The TIAM1 gene and the encoded protein have been implicated in cell proliferation, migration, invasion, and tumor progression in a variety of human cancer." (PMID 41149035, 2025). "Fermt2 and Tiam1 are implicated in cellular migration and invasion, suggesting that disruption of ephrinB2 signaling impairs mechanisms that facilitate tumor cell penetration of vessel walls." (PMID 39489818, 2025). "Circ_0061407 is spliced from the 17 to 20 exons of the TIAM1 transcript, which was frequently reported as a tumour-associated gene." (PMID 38711144, 2024). "By way of example, Malliri and colleagues demonstrated that TIAM1 was an important driver of intestinal tumourigenesis in the Apcmin/+ mouse model, in which tumours arise through sporadic loss of heterozygosity of the Apc gene." (PMID 33397922, 2021). "Here, they demonstrated that TIAM1 loss resulted in a suppression of intestinal tumour initiation, though observed that those tumours that did arise were more invasive." (PMID 33397922, 2021). "Targeting the Tiam1-Rac pathway therapeutically remains a subject of ongoing investigation, due to the dramatic reduction in tumour formation following loss of Tiam1 in animal models." (PMID 33758078, 2021). "Our results also showed that SFRP2 methylation was associated with TIAM1 promoter methylation in CRC tumor area from the > 30th CRC patients." (PMID 32517740, 2020). "Sequencing of the tumor in parallel with peripheral blood revealed the presence of TIAM1 germline variants in at least 5 out of the 12 cases." (PMID 28423360, 2017). "Erg and Tiam1 dysregulation is associated with several tumor types, including AML and B- and T-cell lymphomas." (PMID 29042628, 2017). "T-lymphoma invasion and metastasis-inducing protein 1 (Tiam1) has been implicated in tumor occurrence and progression." (PMID 27562113, 2016). "Overexpression of the T lymphoma invasion and metastasis 1 (Tiam1) protein has been implicated in the migration and invasion of neoplasms." (PMID 26369827, 2015). "We detected the expression of Tiam1 in normal and tumor tissues and determined its association with clinical outcomes in patients with HNSCC." (PMID 26369827, 2015). "Tiam1 has been linked with cancer progression and having growth promoting functions based on the tumor type." (PMID 23950931, 2013). "The postulated effects of miR-31 on SATB2 and TIAM1 are consistent with the associations between miR-31 expression and advanced tumor stage, observed by us and others, but clearly, the regulatory activity of miR-31 is still incompletely understood in CRC." (PMID 23121918, 2012). "Interestingly, the authors observed that whereas Tiam1 deficiency in fibroblasts is associated with increased tumor invasion, Tiam1 expression in cancer cells facilitates tumor growth." (PMID 32604738, 2020). "TIAM1 deletion causes the dedifferentiation of nerve cells and thus leads to tumor occurrence." (PMID 28591696, 2017). "Therefore, screening only for somatic mutations by terms of comparing sequences from blood and tumor would have censored these TIAM1 germline variants." (PMID 28423360, 2017). "Interestingly, A163V TIAM1 variant was heterozygous in blood and became homozygous in the tumor, suggesting a recessive phenotype." (PMID 28423360, 2017). "One plausible explanation is that screening for tumor-specific somatic mutations may have skipped TIAM1 protective germline variants." (PMID 28423360, 2017). "In addition, Tiam1 associated with tumor stage and Ki-67 expression, but negatively correlated with receptor tyrosine-protein kinase erbB-2 (Her2) expression." (PMID 27562113, 2016).
tumor (continued). "We have previously shown that silencing the Rac exchange factor Tiam1 in tumor-associated fibroblasts induces increased invasion and metastasis in epithelial and cancer cells, using different tissue models with a range of technical complexity and biologically relevant tissue context." (PMID 26821678, 2016). "We therefore hypothesized that decreased tumor growth in these mice is due to Tiam1 deficiency in the tumor cells, while the increased tumor invasion is due to Tiam1 deficiency in the tumor stroma, specifically in the fibroblasts." (PMID 26821678, 2016). "The association between Tiam1 expression and tumor position was marginally significant (P = 0.064)." (PMID 26369827, 2015). "In addition, evidence also suggested that expression of Tiam1 is closely associated with lymph node metastasis in other tumor tissues." (PMID 24661909, 2014). "In addition to its role in oncogenic transformation, Tiam1 has also been implicated in the regulation of migration, invasion, and metastasis of tumour cells." (PMID 17003780, 2006). "However, we have chosen to focus on the role of Tiam1 in tumor-associated stroma." (PMID 26821678, 2016). "Additional supporting evidence for our model was recently provided by studies comparing tumour formation in Min/+ mice (with a heterozygous nonsense mutation in the APC gene that leads to constitutive activation of the canonical Wnt pathway) with different Tiam1 backgrounds." (PMID 18826597, 2008). "In OSCC specifically, CAFs can influence tumor cell behavior via secreted factors such as TIAM1, which promotes proliferation, migration, invasion and epithelial–mesenchymal transition (EMT) in OSCC cells." (PMID 41153834, 2025). "Taken together, we confirmed that TIAM1 promoted the migration of tumor cells and inhibited cell apoptosis." (PMID 39418072, 2024). "T lymphoma invasion and metastasis 1 (Tiam1) is a tumor related gene that specifically activates Rho-like GTPases Rac1 and plays a critical role in the progression of various malignancies." (PMID 38017477, 2023). "Tiam1 is specifically expressed in various malignant tumors and is closely related to the proliferation, migration, and invasion of tumor cells." (PMID 38017477, 2023). "In vitro KO of one of Wnt signal-related genes, T-lymphoma invasion and metastasis-inducing protein (TIAM1), increased tumor 5-FU chemical sensitivity." (PMID 37993945, 2023). "Meanwhile, the xenograft tumor model experiment further verified that silencing Tiam1 of Bxpc-3 cell resulted in a corresponding decrease in tumor tissue weight." (PMID 38017477, 2023). "Further validation was conducted in vivo experiments, providing evidence of Tiam1’s promoting role in tumor development." (PMID 38017477, 2023). "Tiam1 is a well-characterized transcriptional activation target of CtBP that drives tumor progression and metastasis in several cancer model systems." (PMID 37707363, 2023). "Analysis of TCGA datasets via the R2 platform also showed that YAP1 and TIAM1 expression exhibited a positive correlation (R > 0.1, p < 0.01) in almost 30% of all tumor patterns (12 out of 34)." (PMID 35773411, 2022). "Conversely, knockdown of TIAM1 in RASAL2-overexpressing MIA PaCa-2 cells with siRNA reduced the ability of tumor cell proliferation, migration and invasion." (PMID 35844783, 2022). "In PDAC, high expression of TIAM1 suggested a poor prognosis and silencing TIAM1 decreased tumor cell proliferation, migration and invasion." (PMID 35844783, 2022). "PDAC expresses a high level of TIAM1 expression and predicts a poor prognosis, while mechanistically silencing TIAM1 decreases tumor cell proliferation, migration and invasion." (PMID 35844783, 2022). "Our current knowledge indicates that Tiam1 regulates different aspects of tumor development, promoting tumor progression or antagonizing tumor invasion, making therapeutic intervention challenging." (PMID 34071831, 2021).
tumor (continued). "ERBB2-positive p140Cap tumor cells show a significant decrease in the activation of Tiam1 and of Rac." (PMID 33079227, 2021). "Downregulation of miR-29c-3p promoted NPC cell migration and invasion by targeting TIAM1; miR-375-3p plays roles as a tumor suppressor by targeting oncogene PDK1, which promotes the proliferation, migration, and invasion of NPC cells." (PMID 34336826, 2021). "The small GTPase RAC1 and its guanine nucleotide exchange factor (GEF) TIAM1 promote cell survival, proliferation, migration, and invasion, processes required for tumor growth and metastasis." (PMID 34758330, 2021). "TIAM1 promotes chemoresistance and tumor invasiveness, and its expression levels are positively correlated to with poor prognosis in solid cancers." (PMID 32411128, 2020). "Two members of the miR-10 family (miR-10a and miR-10b) have been shown to function as tumor suppressors by directly targeting TIAM1." (PMID 32353968, 2020). "SFRP2 methylation was also correlated with T cell lymphoma invasion and metastasis 1 (TIAM1) methylation in tumor area and CCAAT/enhancer-binding protein alpha (C/EBPα) in VAT." (PMID 32517740, 2020). "We demonstrated that the inhibition of TIAM1 enhanced sensitivity to chemotherapeutic drugs and reduced tumor invasiveness in a series of experiments in vitro." (PMID 30890693, 2019). "Once activated, Rab5 recruits a number of interacting proteins, such as Rac1 and Tiam1, which play an important role in tumor metastasis." (PMID 31338333, 2019). "Different aspects of tumor development are influenced by overexpression of Tiam1 in many types of tumors." (PMID 30171257, 2019). "How Tiam1 is involved in tumor formation and metastasis, as well as the parameters that affect its expression, are unclear." (PMID 30171257, 2019). "Consistently, tumor weight of harvested tumors confirmed that animals with TIAM1 suppression demonstrated a superior response to 5-FU compared to controls (p < 0.001)." (PMID 30890693, 2019). "Our study is the first report presenting that RAC1-activation via beta-catenin-VAV2/TIAM1 cascade acts as a downstream signaling event of WP activation in TNBC in the regulation of fibronectin-directed MA tumor cell phenotypes." (PMID 27902969, 2017). "To verify this observation, we reviewed the diagnosis of patients with TIAM1 deletion and to observe the morphological characteristics of tumor cells microscopically." (PMID 28591696, 2017). "SIRT1 has been shown to interact with and activate TIAM1 (T-cell lymphoma invasion and metastasis 1) and Rac1 in tumor cells, in parallel with TIAM1 acetylation." (PMID 29074993, 2017). "Here working out the mechanisms underlying the observed decrease in Rac activation when p140Cap is expressed, we found a significant decrease in the activation of Tiam1 in p140Cap tumour cells." (PMID 28300085, 2017). "We report for the first time that RAC1-activation via beta-catenin-TIAM1/VAV2 cascade acts as a downstream signaling event of WP activation in TNBC in the regulation of fibronectin-directed MA tumor cell phenotypes." (PMID 27902969, 2017). "In cancer cells, Tiam1 expression plays a key role in favoring tumor growth, and its expression in the stroma controls tumor invasion." (PMID 28769537, 2017). "Taken together, these data show that p140Cap interferes with the Rac circuitries that control ERBB2 tumour progression, by binding to Tiam1, leading to both Tiam1 and Rac inactivation." (PMID 28300085, 2017). "Together, our findings suggest that in CRC TIAM1 suppresses tumor progression by regulating YAP/TAZ activity." (PMID 28416184, 2017). "Previously, using recombinant mouse models, we have shown that TIAM1 cooperates with WNT signaling during initiation of intestinal epithelial neoplasia but then appeared to antagonize tumor progression." (PMID 28416184, 2017). "Overexpression of Tiam1 protein participates in many processes underpinning tumor progression, including apoptosis, lymphangiogenesis, invasion and migration." (PMID 27562113, 2016).
tumor (continued). "It was reported to participate in tumor progression and metastasis by activating Rho-like GTPases, specifically the Tiam1-Rac pathway." (PMID 27562113, 2016). "Currently, many studies have reported that Tiam1 participates in several signaling pathways in tumor cells, and plays important roles in cancer progression, metastasis and invasion." (PMID 27562113, 2016). "Tiam1 expression plays an important role in tumor progression and metastasis by activating Rho-like GTPases, specifically the Tiam1-Rac pathway, which participates in cell migration, invasion and metastasis." (PMID 27562113, 2016). "Much of the work on Tiam1 has focused on its role within cancer cells, and Tiam1 expression in tumor cells is required for facilitating tumor growth." (PMID 26821678, 2016). "To determine the role of 14-3-3ζ in loss of Par3-induced Tiam1-Rac1 and JAK-STAT activation, we used shRNA to inhibit the expression of 14-3-3ζ in tumor cells." (PMID 27588399, 2016). "Many groups have investigated Tiam1 expression in different tumor cell models and human tumor specimens." (PMID 26821678, 2016). "And more notably, high expression of Tiam1 in tumor cells, implying a poor prognosis, has been observed in several solid tumors." (PMID 24661909, 2014). "T lymphoma invasion and metastasis 1 (Tiam1) is a potential modifier of tumor development and progression." (PMID 24069171, 2013). "Oncogenic potential of Tiam1 was found to be present in various tumors with respect to the tumor grade and stage." (PMID 23950931, 2013). "On molecular basis, in vitro studies provided insights into the effect of Tiam1 carcinogenesis and tumor invasion." (PMID 24069171, 2013). "On the other hand, there are also numerous reports that supported the role of Tiam1 in promotion of malignant transformation, tumor proliferation, invasion, and metastasis." (PMID 24069171, 2013). "Although most evidence supports a role for Tiam1 in cancer progression, it appears to have both growth-suppressive and growth-promoting functions, depending on the tumor type examined." (PMID 20819206, 2010). "Collectively, these observations suggest that the contribution of Tiam1 to tumorigenesis is dependent on the tumor type, the degree of tumor progression, and the signaling context." (PMID 20819206, 2010). "Deficiency of the Rac GEF Tiam1 in MMTV-Neu mice delayed tumor onset and decreased metastasis suggesting that Rac1 activity plays a causal role in MMTV-Neu induced tumor formation and progression." (PMID 20860838, 2010). "Elevated Rac1 activity promotes transformation and metastasis, and deficiency of the RacGEF, Tiam1, inhibits MMTV-Neu tumor formation." (PMID 20860838, 2010). "Tumour tissue exhibited high levels of all three Rho activators Trio, Vav1 and TIAM-1 compared with normal background breast tissue, reaching a level of significance for the GEF Trio (p = 0.013)." (PMID 18925966, 2008). "The Rac-specific guanine nucleotide exchange factor, Tiam1, plays a major role in oncogenicity, tumour invasion and metastasis but its usefulness as a prognostic marker in human cancer has not been tested yet." (PMID 17003780, 2006). "While the tumor-suppressive roles of TIAM1 and RAP1GAP have been previously established, our findings reveal that the overexpression of GPX3 and JUN significantly impairs the proliferative and migratory capacities of TC cells, underscoring their potential as therapeutic targets." (PMID 40092686, 2025). "Moreover, CD10 (MME) positive myCAFs were found as a novel tumor suppressed CAF subclusters, while KLF4 positive and TIAM1 positive iCAFs were considered as tumor promoted CAF subclusters." (PMID 40303408, 2025). "This enables TIAM1 to play an important role in tumor metastasis and invasion processes." (PMID 39596516, 2024). "Taken together, these findings may suggest that TIAM1 plays a significant role in the tumor microenvironment signaling pathway by activating cell proliferation and tumorigenic potential." (PMID 38003292, 2023).
tumor (continued). "Based on this initial observation, further work will be required to determine if strategies for targeting TIAM1 could be developed as potential new tumour-specific therapeutic approaches for a defined subset of HCC patients." (PMID 37047360, 2023). "Additionally, our clinicopathological analysis revealed a positive correlation between Tiam1 expression and tumor grade (p = 0.016) as well as lymph node (LN) metastasis (p = 0.033), as illustrated in the forest plot." (PMID 38017477, 2023). "Furthermore, the strongly positive rate of Tiam1 expression in PC tissues (49/66, 74.2%) was significantly higher compared to that in non-tumor tissues (4/54, 7.4%, p < 0.05)." (PMID 38017477, 2023). "In addition, the expression levels of ORC1, TNFRSF12A, TRAF1 and TIAM1 were also positively correlated with tumor grade to a certain extent." (PMID 37005685, 2023). "In addition, co-expression of anti-miR-590-5p and si-Tiam1 largely reversed the tumor-promoting effect." (PMID 38017477, 2023). "Therefore, RASAL2 increased TIAM1 expression and promoted the malignancy of tumor cells by upregulation of YAP1." (PMID 35844783, 2022). "This leaves the possibility that the dual function of Par3 could be influenced by Tiam1/Rac1 depending on tumor type." (PMID 35875120, 2022). "Together, these indicate a pathway by which Tiam1 depletion could enhance tumour progression, and highlights a need for a more detailed understanding of Tiam1 signalling to separate its pro- and anti-tumourigenic properties." (PMID 33758078, 2021). "Initial studies of Tiam1-dependent activation of Rac in cancer showed that it was required for Ras-induced skin tumors due to an increased apoptosis rate in epidermal keratinocytes during tumor initiation." (PMID 34071831, 2021). "However, in > 30th CRC group, SFRP2 methylation was positively correlated with promoter methylation of TIAM1 in tumor area (p < 0.05)." (PMID 32517740, 2020). "To summarize, all data illustrated that miR-1271-5p might function as a tumor-suppressive factor in OC through targeting TIAM1." (PMID 32948241, 2020). "Our study indicates that TIAM1 is a potential therapeutic target which could target both tumor cells and CAFs." (PMID 30890693, 2019). "Enhanced Tiam1/Rac1 signaling may increase the transcription of Wnt target genes to promote tumor initiation and progression." (PMID 30171257, 2019). "Tiam1/Rac1 signaling is critically involved in tumor cell progression, invasion, and metastasis." (PMID 29416753, 2018). "TNBC patients’ (cBioPortal) tumor expressed alterations of TIAM1 and VAV2 genes." (PMID 27902969, 2017). "Analysis of paired samples (peripheral blood plus tumor from same patient) revealed no increase of TIAM1 variant allele ratios in 4 tumors." (PMID 28423360, 2017). "The role of TIAM1 in the invasion and metastasis of tumor cells has been well documented." (PMID 28423360, 2017). "All these findings indicate that Tiam1 expression might be a new and independent predictor of prognosis in various tumors, and Tiam1 may be a potential target for tumor therapy." (PMID 27562113, 2016). "Moreover, Tiam1 has been reported to participate in the regulation of the tumor microenvironment by promoting the formation of E-cadherin-mediated cell-cell adhesion." (PMID 27562113, 2016). "However, in mice genetically lacking Tiam1, the tumors that do develop are more invasive, conceptually inconsistent with the requirement for Tiam1 for tumor growth and functionally inconsistent with how human tumors behave clinically." (PMID 26821678, 2016). "Of note, none of these data sets found significant changes in Tiam1 expression, which may indicate a post-translational mechanism for Tiam1 downregulation in the tumor microenvironment." (PMID 26821678, 2016). "Additionally, several studies reported the role of Tiam1 in the promotion of malignant transformation, tumor proliferation, invasion and metastasis." (PMID 27562113, 2016).